IDE (insulin degrading enzyme)
Diseases named in the same sentence as IDE in open-access papers (continued):
Sharing a sentence is not in itself a finding about the gene and the disease.
Hyperinsulinemia (33 papers, 2011 to 2025). An increased concentration of insulin in the blood. "IDE-deficient mice show increased cerebral Aβ levels along with hyperinsulinemia and glucose intolerance, while amyloid plaque formation is decreased in the brain tissue of IDE-overexpressing animals." (PMID 34831163, 2021). "It has been suggested that hyperinsulinemia is associated with reduction of amyloid metabolism, due to downregulation of insulin-degrading enzyme (IDE) levels in the brain." (PMID 26060494, 2015). "Consistent with its known functional role, IDE deficiency led to significant hyperinsulinemia at all ages examined (2, 4, and 6 months)." (PMID 21695259, 2011). "Since IDE-deficient mice show accumulation of Aβ protein, hyperinsulinemia and glucose intolerance enhancing or emulating the activity of IDE may lower the Aβ burden and may be of interest to pursue as an AD-treatment." (PMID 28219449, 2017). "Indeed, IDE deficient mice demonstrate increased cerebral accumulation of endogenous Aβ with hyperinsulinemia and glucose intolerance, and IDE overexpression ameliorates Aβ pathology, suggesting a link between insulin metabolism and Aβ degradation." (PMID 25368578, 2014). "Indeed, IDE knockout causes hyperinsulinemia and hyperglycemia in mice." (PMID 35350789, 2022). "Tauroursodeoxycholic acid (TUDCA) has been shown to activate the S1PR2 signaling pathway, thereby enhancing the activity of the insulin-degrading enzyme (IDE) and effectively ameliorating hyperinsulinemia and insulin sensitivity." (PMID 40807240, 2025). "It is well-known that the insulin-degrading enzyme (IDE) represents the link and the key factor in the crosstalk between hyperinsulinemia and AD." (PMID 40943177, 2025). "In IDE knockout mouse models, insulin degradation in liver and brain tissues is reduced by approximately 58–72%, resulting in chronic hyperinsulinemia and significantly elevated Aβ levels in the brain." (PMID 40724942, 2025). "Hyperinsulinemia also impairs Aβ clearance, as both are degraded by insulin-degrading enzyme (IDE), and, during periods of high brain insulin, IDE will preferentially bind insulin." (PMID 38540695, 2024). "In one study, they demonstrated how IDE regulates Aβ levels in neuronal cells, with IDE knockout mice displaying hyperinsulinemia, glucose intolerance, and an increased accumulation of cerebral Aβ." (PMID 38255204, 2024). "The mechanism of the hyperinsulinemia-induced development of AD involves the insulin-degrading enzyme (IDE) and the inhibition of Akt, which leads to both Aβ plaque formation and tau hyperphosphorylation, respectively." (PMID 37372995, 2023). "As an initial approach to help elucidating the function of IDE on insulin metabolism in vivo, several laboratories developed mice with pancellular deletion of IDE (IDE-KO) and found age-dependent hyperinsulinemia and glucose intolerance." (PMID 35832432, 2022). "TUDCA attenuated hyperinsulinemia and improved glucose homeostasis in aged mice, by enhancing liver insulin-degrading enzyme (IDE) expression and insulin clearance." (PMID 36564463, 2022). "Aβ can be degraded by the insulin-degrading enzyme (IDE), which can become less active in response to hyperinsulinemia." (PMID 36678547, 2022). "Another suggested mechanism in the link between peripheral hyperinsulinemia and AD is the accumulation of Aβ due to direct competition of insulin-degrading enzyme (IDE) through which Aβ degradation is attenuated, thereby increasing tau formation." (PMID 35661882, 2022). "Hyperinsulinemia has been linked to both CMD dysfunction and AD pathology, and it highlights the close relationship between Aβ and insulin via insulin degrading enzyme (IDE)." (PMID 34497507, 2021). "Studies on an enzyme called insulin-degrading enzyme (IDE), which breaks down both insulin and Aβ peptide, showed that in hyperinsulinemia, IDE shifts towards degrading insulin more than Aβ peptide which leads to Aβ peptide accumulation." (PMID 32190448, 2020).
Hyperinsulinemia (continued). "A previous study involving rats treated with the same dexamethasone protocol demonstrated that the insulin-degrading enzyme activity in the liver is reduced in GC-treated rats, explaining, in part, the hyperinsulinemia observed in these animals." (PMID 30532777, 2018). "Knockout of IDE gene leads to hyperinsulinemia in mice from impaired insulin clearance in multiple tissues." (PMID 24740421, 2014). "IDE knockout mice also show accumulation of endogenous Aβ, hyperinsulinemia and glucose intolerance." (PMID 22870279, 2012). "Subsequently, mice with homozygous deletion of the IDE gene (IDE-KO mice) were found to exhibit pronounced glucose intolerance as well as hyperinsulinemia." (PMID 21695259, 2011). "Insulin signalling induces the expression of the insulin-degrading enzyme (IDE), which is involved in both insulin and Aβ degradation; hyperinsulinemia might determine a competitive inhibition for IDE-dependent Aβ degradation, leading to Aβ accumulation." (PMID 33597002, 2021). "Inactivation of IDE activity leads to hyperinsulinemia in gene knockout mice." (PMID 24740421, 2014). "A recent study indicates that the diabetic phenotype of IDE knockout mice is an emergent compensatory response to chronic hyperinsulinemia, but not a direct consequence of IDE deficiency." (PMID 22870279, 2012). "Our results indicate that the diabetic phenotype in IDE-KO mice is not a primary consequence of IDE deficiency, but is instead an emergent compensatory response to chronic hyperinsulinemia resulting from complete deletion of IDE in all tissues throughout life." (PMID 21695259, 2011). "Up-regulation of IDE activity may help to control hyperinsulinemia in the disease." (PMID 24740421, 2014). "Both insulin and beta amyloid are degraded by the insulin-degrading enzyme (IDE); thus, hyperinsulinemia present in DM patients may competitively affect the increase in beta amyloid accumulation." (PMID 41295439, 2025). "Hyperinsulinemia is a character of DIO mice, and the role of IDE in the hyperinsulinemia remains largely unknown." (PMID 24740421, 2014). "In view of IDE-mediated regulation of primary cilium in α-cells, metabolic phenotypes of hyperglucagonemia and hyperinsulinemia seen in A-IDE-KO mice could be attributed to the absence of cilia leading to loss of cross regulation of β- and α-cells." (PMID 35832432, 2022).
Glucose intolerance (14 papers, 2011 to 2025). Glucose intolerance (GI) can be defined as dysglycemia that comprises both prediabetes and diabetes. "Loss-of-function mutations of IDE in rodents exhibit glucose intolerance and accruement of Aβ aggregates, whereas, IDE action revealed opposite results." (PMID 31293412, 2019). "In humans and rodents, genetic data and deletion experiments suggest a role of IDE in glucose homeostasis: IDE gene knockout in mice results in glucose intolerance, though the mice remain normoglycemic and are only slightly hyperinsulinemic." (PMID 37371470, 2023). "Interestingly, the level of glucose intolerance of Ide−/− mice was similar to the one of parallel bred WT mice of the same genetic background treated with 1, suggesting that the effect of short-term IDE inhibition in WT mice is similar to that of life-long IDE deficiency." (PMID 26394692, 2015). "Unlike total IDE knockout mice, which often show systemic metabolic disturbances, B-IDE-KO mice display only mild glucose intolerance, with no significant changes in fasting glucose levels." (PMID 40724942, 2025).
Cognitive impairment (12 papers, 2014 to 2024). Abnormal cognition is characterized by deficits in thinking, reasoning, or remembering. "CK has also shown positive effects on vascular dementia by reducing the Amyloid β1-42 deposition caused by chronic cerebral hypoperfusion and improving cognitive impairment through the upregulation of pSer9-Glycogen synthase kinase 3β (pSer9-GSK3β) and the insulin degrading enzyme (IDE)." (PMID 37511939, 2023). "Interestingly, in human diabetic patients with mild cognitive deficits, Pio treatment improved peripheral insulin sensitivity, as well as plasma levels of Aβ and the insulin degrading enzyme." (PMID 37190025, 2023). "The insulin-degrading enzyme (IDE), a molecule promoting the degradation of amyloid-β in the brain and improving cognitive impairment in AD patients, modulates microglial activity." (PMID 39081666, 2024).
amyloid (8 papers, 2011 to 2025). "Insulin degrading enzyme (IDE; also known as amyloid-beta degrading protease) has been shown to be important for amyloid clearance and IDE levels are decreased in AD patients." (PMID 36482297, 2022). "Other studies hypothesised an increased production of amyloid plaques either directly or through binding to insulin-degrading enzyme, or induction of systemic inflammatory cytokines." (PMID 40222838, 2025). "Notably, rTMS inhibits BACE1 expression and increases the ratio of insulin-degrading enzyme (IDE), improving both the production and clearance of amyloid load by enhancing brain drainage pathways." (PMID 40142358, 2025).
neuroblastoma (6 papers, 2011 to 2022). Neuroblastoma (NB) is the most common solid, extracranial childhood tumor. "Interestingly, it was evaluated on neuroblastoma cells, in which IDE overexpression has been linked to more aggressive tumors and progression, proliferation and viability." (PMID 35406791, 2022). "In line, IDE gene expression was also significantly reduced in human neuroblastoma PS1 knockout cells." (PMID 33128835, 2020). "Measuring the endogenous expression of neprilysin and insulin-degrading enzyme (IDE)—proteases involved in Aβ degradation—in human neuroblastoma SH-SY5Y cells, the expression of neprilysin was reduced by CM from HBMVECs with H/R treatment or with Sirt1 siRNA transfection." (PMID 33318474, 2020).
Obesity (6 papers, 2015 to 2021). Accumulation of substantial excess body fat. "IL-6 has been examined since it is positively associated with the expression of the insulin-degrading enzyme (IDE), where the deficiency of IDE is related to obesity and T2DM." (PMID 34099024, 2021). "Interestingly, here we demonstrate that reduced insulin degrading-enzyme (IDE) levels in HFS diet-induced obesity is a critical component in liver pathology." (PMID 31372175, 2019). "IDE malfunction has been identified in obesity and type 2 diabetic models." (PMID 31156453, 2019).
dementia (5 papers, 2008 to 2024). Loss of intellectual abilities interfering with an individual's social and occupational functions. "It has been proposed that the insulin‐degrading enzyme (IDE) plays a significant role in the pathophysiology of HZ dementia." (PMID 38482136, 2024). "Impaired functioning of proteins responsible for Aβ clearance such as insulin degrading enzyme (IDE) is also accepted to aggravate AD pathogenesis, resulting in neuronal loss with consequential dementia and death." (PMID 21931647, 2011). "Insulin degrading enzyme (IDE) degrades amyloid β (Aβ), which may inhibit the accumulation of Aβ in a brain affected with dementia of Alzheimer's type (DAT)." (PMID 19415148, 2008).
Hyperglycemia (4 papers, 2014 to 2022). An increased concentration of glucose in the blood. "HFD increased body weight-induced hyperglycemia and dyslipidemia and caused resistance to insulin while reducing the level of insulin-degrading enzyme (IDE)." (PMID 36304965, 2022). "Hyperglycemia impairs insulin-induced insulin-degrading enzyme (IDE) activity in the liver cell model, and hepatic insulin clearance has been closely related to metabolic syndrome components." (PMID 35551683, 2022).
Hypoglycemia (2 papers, 2018 to 2025). A decreased concentration of glucose in the blood. "Our group has been exploring an alternative approach to boosting insulin signaling that obviates the risk of hypoglycemia: namely, pharmacological inhibition of insulin-degrading enzyme (IDE), the principal protease implicated in the catabolism and inactivation of insulin." (PMID 29447281, 2018). "Importantly, mice with genetic deletion of IDE are viable; thus—unlike insulin—IDE inhibitors possess no intrinsic risk of triggering life-threatening hypoglycemia." (PMID 29447281, 2018). "Interestingly, ML345 did not induce hypoglycemia or impair glucose tolerance under our experimental conditions, despite its reported IDE inhibitory activity." (PMID 41231359, 2025).
varicella zoster virus infection (2 papers, 2009 to 2014). "However, over the last decade, several experimental findings have established that IDE is also involved in a wide variety of physiopathological processes, including ubiquitin clearance and varicella zoster virus infection." (PMID 25071716, 2014).
Autoimmunity (1 paper, 2024). The occurrence of an immune reaction against the organism's own cells or tissues. "Conversely, the unaltered diabetogenic effect of IDE deficiency in mice reconstituted with 8.3 bone marrow confirmed the selective impact of this enzyme on insulin-specific CD8+ T cell responses, leading to reduced autoimmunity in Ide-/- mice." (PMID 39600694, 2024).
cerebral amyloid angiopathy (1 paper, 2022). "Memantine also reduces cerebrovascular Aβ and hemosiderin deposits in APP23 transgenic mice with cerebral amyloid angiopathy, by enhancing Aβ-cleaving insulin degrading enzyme (IDE) expression." (PMID 35330211, 2022).
COVID-19 (1 paper, 2022). A disease caused by infection with severe acute respiratory syndrome coronavirus 2. "Notably, IDE’s surface expression was upregulated on monocytes from COVID-19 patients at diagnosis, and it was increased in more severe patients." (PMID 36232381, 2022). "To gain insights into the function of IDE on COVID-19 infection, we analyzed the expression levels of IDE in peripheral blood mononuclear cells (PBMC) isolated from healthy donors and COVID-19 patients, both at diagnosis and 3 months after hospital discharge." (PMID 36232381, 2022).
diarrheal disease (1 paper, 2016). The condition of having at least three loose or liquid bowel movements each day. "Furthermore, altering the activities of angiotensin-converting enzymes (ACEs) and endothelin-converting enzymes or insulin-degrading enzyme would have potential to affect blood pressure or insulin levels, which would not be desirable in diarrheal disease states." (PMID 26907621, 2016).
glaucoma (1 paper, 2025). Increased pressure in the eyeball due to obstruction of the outflow of aqueous humor. "Elevated ZAG and reduced insulin degrading enzyme levels have been detected in the tear fluid of patients with glaucoma." (PMID 41154592, 2025).
glioma (1 paper, 2020). A benign or malignant brain and spinal cord tumor that arises from glial cells (astrocytes, oligodendrocytes, ependymal cells). "DDT also increases Aβ levels in H4 glioma cells with a APPSwe transgene via elevation of APP and BACE1, while decreasing the levels of Aβ-clearing ATP-binding cassette transporter A1 (ABCA1) and inhibiting the activity of Aβ-degrading insulin-degrading enzyme (IDE)." (PMID 32218337, 2020).
Impaired glucose tolerance (1 paper, 2011). An abnormal resistance to glucose, i.e., a reduction in the ability to maintain glucose levels in the blood stream within normal limits following oral or intravenous administration of glucose. "Consistent with an age-dependent transition from improved to impaired glucose tolerance, 4-mo-old IDE-KO mice showed an intermediate phenotype." (PMID 21695259, 2011).
insulinoma (1 paper, 2015). "Since inhibition of IDE also accelerates hIAPP amyloid formation in insulinoma cells, we used an shRNA specific to rat IDE (IDEi) as a positive control and a nonsilencing shRNA (NSi) as a negative control." (PMID 26191799, 2015).
iron deficiency (1 paper, 2021). "Therefore, we suggest that ABI/VP1 TF gene identified in our research could play an indirect role in salinity tolerance via activating IDE-type genes which in turn transactivates the Fe deficiency-induced gene(s) to overcome iron deficiency by absorption higher amounts of Fe under salt stress." (PMID 33420909, 2021).
ischemia (1 paper, 2024). A hypoperfusion of the BLOOD through an organ or tissue caused by a PATHOLOGIC CONSTRICTION or obstruction of its BLOOD VESSELS, or an absence of BLOOD CIRCULATION. "Thus, the heightened chiro-inositol level, facilitated by the downregulation of insulin-degrading enzyme, could explain the resilience of the A-to-I–locked state against mitochondrial insults such as ischemia/reperfusion injury and direct ATP synthase inhibition." (PMID 38954486, 2024).
melanoma (1 paper, 2010). A malignant, usually aggressive tumor composed of atypical, neoplastic melanocytes. "Previous studies using fibroblasts and melanoma cells suggested that IDE functions as a cellular receptor for gE enhancing VZV infectivity and cell-to-cell spread in these two cell types." (PMID 20593027, 2010).
prediabetes (1 paper, 2026). "Notably, the genetic regulation of IC by insulin‐degrading enzyme (IDE) is compromised as prediabetes advances." (PMID 41133433, 2026).
schizophrenia (1 paper, 2023). A major psychotic disorder characterized by abnormalities in the perception or expression of reality. "To date, no studies have specifically investigated the relationship between polymorphisms of the IDE gene and schizophrenia." (PMID 37515308, 2023). "Our results confirm the role of the IDE gene in schizophrenia pathogenesis and suggest that future research should investigate the relationship between miRNA and estrogen influence on IDE expression in schizophrenia pathogenesis." (PMID 37515308, 2023).
infection (6 papers, 2012 to 2024). The state of being infected such as from the introduction of a foreign agent such as serum, vaccine, antigenic substance or organism. "The loss of IDE’s function inhibited VZV infection, whereas its gain-of-function resulted in increased entry and enhanced infection with both the cell-free and cell-associated virus." (PMID 36232381, 2022). "Evidence shows that IDE is a VZV receptor mediating infection and cell‐to‐cell transmission." (PMID 38482136, 2024). "VZV gE may have gD-like functions during initiation of infection through binding the insulin-degrading enzyme (IDE), a proposed VZV receptor." (PMID 23435239, 2013). "Furthermore, there is evidence that insulin degrading enzyme (IDE) binding to VZV gE is required for infection in an in vitro system, and acts as a receptor for spread of the virus from cell to cell." (PMID 22754650, 2012). "As a promiscuous metalloprotease, IDE can degrade a wide range of substrates, including CCL3 (i.e., macrophage inflammatory protein-1α (MIP-1α)) and CCL4 (MIP-1β), which are small peptides required for the recruitment of immune cells to the site of infection or inflammation." (PMID 36232381, 2022).